NRAS (NRAS proto-oncogene, GTPase)
Diseases named in the same sentence as NRAS in open-access papers (continued):
Sharing a sentence is not in itself a finding about the gene and the disease.
melanoma (continued). "We observed highly increased p-ERK levels in response to a 20 h treatment with the eIF4A helicase inhibitor in both melanoma subtypes, despite the presence of strong oncogenic BRAF and NRAS mutations already highly activating the ERK pathway in these cells." (PMID 39436655, 2024). "We therefore explored the role of DUSP1/p38 MAPK in NRAS-mutant melanomas and evaluated the effect of corin in dose-response assays." (PMID 38300709, 2024). "The main finding is that the two main oncogenic drivers in melanoma, BRAF V600 and NRAS Q61 hotspot mutations, result in different underlying signaling biologies requiring different treatment regimes using the same drugs." (PMID 39199684, 2024). "Of note, clinically relevant targets such as BRAF and NRAS have comparable incidences (53–58% for BRAF and 23–28% for NRAS, respectively) thus suggesting the value of larger scale sequencing in the melanoma context." (PMID 38184610, 2024). "In contrast, NRAS-mutant melanoma cells displayed a paradoxical activation of pERK1/2 after treatment with 1–10 μM vemurafenib, which is in line with previous reports." (PMID 38839106, 2024). "Studies have shown that silencing ROCK1 via genetic modulation or inhibition with GSK269962A (a selective ROCK1 inhibitor) enhances the effectiveness of BRAF and MAPK inhibitors against BRAF and NRAS mutant melanoma cells." (PMID 39273383, 2024). "RAC1 mutations are insufficient to drive melanoma and are almost always found with other activating MAP kinase hot spot mutations, most frequently NRAS (47%), BRAF, or NF1." (PMID 40396280, 2024). "In turn, the PIK3CA E545K mutation pre-existing in NRAS-driven melanoma was indicated as an aberration that caused resistance to MEK and CDK4/6 inhibitors in melanoma patients." (PMID 39340537, 2024). "Taken together, our data describe how NRAS mutant melanoma adapt to CDK4/6 and MEK inhibition by triggering an EMT programme." (PMID 37420093, 2023). "Mutations of the oncogenes v-raf murine sarcoma viral oncogene homolog B1 (BRAF) and neuroblastoma RAS viral oncogene homolog (NRAS) are the most frequent genetic alterations in melanoma and are mutually exclusive." (PMID 36982192, 2023). "In the case of melanoma, mutations in another RAS gene, NRAS, have been reported as one of the resistance mechanisms to BRAF inhibition." (PMID 36967525, 2023). "In the cBioPortal database, we found a frequency of 0.5–1.2% samples with CRKL and MAPK1 co-amplification with a trend to mutual exclusivity with KRAS, NRAS and BRAF mutations in NSCLC and melanoma." (PMID 37443114, 2023). "We show that BRAF and NRAS mutant melanomas have diverse mean sizes, but size uniformity is maintained." (PMID 36696495, 2023). "A preclinical study using NRAS-mutant human melanoma cell lines revealed synergistic effects on both apoptosis and cell-cycle arrest with corresponding tumor regression." (PMID 37370834, 2023). "Activating mutations in the NRAS and BRAF genes play an important role in promoting the progression of melanoma." (PMID 37221594, 2023). "In vivo studies using colorectal, lung, and melanoma (NRASQ61K SKMel-30) models showed dose-dependent tumor growth inhibition across KRAS- and NRAS-mutated tumors." (PMID 37370834, 2023). "It was shown that NRAS mutant melanoma cells can keep their malignant properties after knockout of BRAF and CRAF, being dependent on ARAF to sustain ERK signaling." (PMID 37627277, 2023). "In a study investigating the genomic profile of 122 acral melanomas using DNA sequencing, mutations in BRAF (21.3%), NRAS (27.9%), and KIT (11.5%) were identified." (PMID 36980308, 2023). "Deletion of negative ERK regulators, including DUSP4, DUSP6, and PEA15, induced cell death in BRAF and NRAS mutant melanomas due to unrestrained activation of ERK." (PMID 37803324, 2023). "The NRAS gene, which is an additional stimulator of the MAPK pathway, is mutated in 15–20% of melanomas." (PMID 36834954, 2023).
melanoma (continued). "Both IL-17 and TH17 cell differentiation GES were among the most significantly over-represented pathways in MAPK-mutated (n = 77 BRAF hotspot-mutant, n = 42 NRAS hotspot-mutant, n = 1 NF1-mutant) melanomas compared to triple-WT melanomas (n = 36)." (PMID 37525015, 2023). "Because hematopoietic cells are small and difficult to image, we performed live-cell imaging of GFP-NRAS in SK-MEL-147 cells, a melanoma cell line that harbors an NRASQ61R mutation, the same NRAS mutation found in OCI-AML3." (PMID 37317963, 2023). "In this real‐world study, melanoma patients with BRAF, KIT, or NRAS mutations treated with anti‐PD‐1 adjuvant monotherapy had no statistical difference of DFS compared to patients received IFN or observation." (PMID 37403699, 2023). "In contrast, other studies were able to prove the role of ER stress in the induction of apoptosis by BRAF inhibitors as a strategy to similarly treat NRAS-mutant melanoma." (PMID 38067230, 2023). "To identify the mechanism of MEKi resistance, we first assessed activation of the ERK and AKT pathways, since NRAS activates both pathways in NRAS-mutant melanoma cells." (PMID 36765910, 2023). "Factors which are driving melanoma drug resistance mainly involve mutations in the mitogen-activated protein kinase (MAPK) pathway, e.g., BRAF splice variants, neuroblastoma RAS viral oncogene homolog (NRAS) amplification or parallel survival pathways." (PMID 37509693, 2023). "Its activity was demonstrated in BRAF-mutant, NRAS-mutant, and WT melanoma cell lines, as well as in xenograft melanoma models." (PMID 36902392, 2023). "Previous studies describe synergistic anti-tumor activity by combining the inhibition of PLK1 and NOTCH in melanoma or PLK1 and MEK in NRAS-mutated melanoma." (PMID 36768289, 2023). "Here, using both loss-of-function and gain-of-function approaches, we show that ABL1/2 and DDR1 are critical nodes during NRAS-mutant melanoma intrinsic and acquired MEK inhibitor (MEKi) resistance." (PMID 36765910, 2023). "We examined RNA-seq data in clinical trial samples from patients harboring NRAS-mutant melanomas who had been treated with a MEKi." (PMID 36765910, 2023). "Our data suggest that the mechanism of action of p38–induced tumor suppressive effects in NRAS-mutant melanoma is through the activation of mTOR pathway, which in turn leads to suppressed autophagy and changes the dynamics of actin cytoskeleton." (PMID 36765834, 2023). "To further characterize the transcriptional effects, we performed bulk RNA-seq analyses on two patient-derived NRAS-mutant melanoma cell lines (130429 and 160915)." (PMID 36765834, 2023). "The Cancer Genome Atlas classifies the genome mutations that occur in melanoma into four subtypes: mutant BRAF, mutant NRAS, mutant NF1, and triple-wild-type." (PMID 37445615, 2023). "NRAS‐mutant melanoma is a distinct cohort which comprises 13% to 20% of this disease, and appears to confer a poor prognosis." (PMID 37403699, 2023). "The MEK inhibitor binimetinib shows an overall response rate of 15% in patients with NRAS-mutant melanoma, providing a backbone for combination strategies." (PMID 38067230, 2023). "In the clinic, a patient with advanced NRAS-mutant melanoma was treated as an individual healing attempt based on previous results." (PMID 38067230, 2023). "Current management of NRAS mutant melanoma mainly relies on MEK inhibitors (MEKi) and immune checkpoint blockade (ICB) therapy." (PMID 37083947, 2023). "A partial response rate of 20% and 3.7 months of PFS in NRAS‐mutant melanoma were reported in a phase II study using MEK inhibitor binimetinib." (PMID 37403699, 2023). "Recently, a serine/threonine kinase, STK19, has been identified as a new NRAS activator by phosphorylating NRAS and subsequently enhancing the downstream NRAS-driven malignant transformation in melanoma cells." (PMID 37221195, 2023).
melanoma (continued). "The aim of this study was to understand why MEKi are ineffective in NRAS-mutant melanomas with the long-term goal of identifying new treatment regimens." (PMID 36765910, 2023). "Because p38 regulates more than 60 proteins, delineating the downstream targets and effect of p38 activation on MAPK signaling in NRAS-mutant melanoma cells is imperative to better target these cells." (PMID 36765834, 2023). "As the mitogen-activated protein kinase (BRAF-MAPK) signaling pathway is frequently activated in melanoma, we analyzed TERT in melanoma subtypes with hotspot mutations in BRAF, RAS (NRAS, KRAS, HRAS) and NF1 genes in the SKCM cohort." (PMID 37418389, 2023). "Among the MEK inhibitors, binimetinib has emerged as a notably effective choice for treating NRAS-mutant melanoma." (PMID 38067230, 2023). "Only 10–20% of melanomas (particularly in amelanotic nodular variants) exhibited activating RAS mutations, with NRAS mutations becoming the most prevalent." (PMID 37102943, 2023). "BRAFV600E/K inhibitors such as encorafenib have been shown to activate the MAPK pathway in NRAS-mutant melanoma cells by increasing phosphorylated ERK (pERK)." (PMID 38067230, 2023). "Although both BRAF-mutant and NRAS-mutant melanomas have activation of the MEK/ERK pathway, MEK inhibitors (MEKi) are only effective for the BRAF-mutant subtype." (PMID 36765910, 2023). "Further investigation to modulate a combination of these compounds along with FDA approved drugs like MEK inhibitors can be a novel strategy to treat NRAS mutant melanomas." (PMID 36765834, 2023). "Cutaneous melanoma was the primary in 270 patients (84.9%), 171 (53.8%) had BRAF/NRAS wild-type variants, 113 (35.5%) had resected stage IIIB, and 124 (39.0%) had resected stage IIIC melanomas (AJCC Cancer Staging Manual, version 8)." (PMID 37535354, 2023). "Some of the most commonly occurring somatic alterations in melanoma include mutations in the BRAF, NRAS, and KIT genes." (PMID 37504268, 2023). "Class 2 BRAF mutations were also significantly more prevalent in HRAS (8%) compared to KRAS- and NRAS-mutant melanoma." (PMID 37503077, 2023). "Genomic alterations of BRAF and NRAS are oncogenic drivers in malignant melanoma and other solid tumors." (PMID 37219686, 2023). "Here we characterised the response of three different NRAS mutant melanoma cell lines to a combination of CDK4/6 and MEK inhibitors over 33 days." (PMID 37420093, 2023). "In melanoma with CDKN2A germline mutations, there are usually somatic mutations in BRAF and NRAS genes, NRAS mutations being the most common ones." (PMID 36805510, 2023). "Molecularly, melanomas harbor somatic ‘driver mutations’ that are mutually exclusive: 50% present gain‐of‐function BRAF mutations, while another 25% exhibit NRAS mutations." (PMID 36744297, 2023). "According to multiple studies, RAF/RAS isoforms activate the Nrf2 pathway, and BRAF/NRAS mutant melanomas express more Nrf2." (PMID 36747120, 2023). "The relevance of this pathway is underlined by the fact that hyperactivity of the ERKs through mutations in NRAS, its negative regulator NF1, or its downstream effector BRAF are causally related to ~75% of sporadic melanomas." (PMID 37762683, 2023). "NRAS and BRAF mutations are almost always mutually exclusive, where NRAS mutations occur in about 20% of melanoma cases." (PMID 37762707, 2023). "We modeled BRAFV600E and NRAS-mutant tumors, which form most patient cutaneous primary melanomas in the clinic, and considered a range of further molecular alterations, namely, MITF status, loss of PTEN, presence of BRAFV600E, and loss of CDKN2A." (PMID 37043573, 2023). "Contrary to BRAF-mutant melanomas, patients with NRAS-mutant melanoma tend to be older and have chronic sun UV exposure." (PMID 37239381, 2023). "This suggests compensatory functions of other RAF proteins, such as the ones reported in NRAS-mutant melanoma, or a more specific function of ARAF, which is able to activate RAS by antagonizing NF1 binding." (PMID 37020037, 2023).
melanoma (continued). "This study aimed to assess the efficacy and safety of BRAFi + MEKi combination therapy in NRAS-mutant melanomas." (PMID 38067230, 2023). "For example, NRAS mutations such as NRASQ61K and NRASA146T were detected in dabrafenib-resistant melanoma patient tumors and cell lines." (PMID 37834284, 2023). "Several mutations, known as driver mutations (BRAF, NRAS, KIT, GNAQ, GNA11, NF1, and TERT), define most of the molecular subtypes of melanoma." (PMID 37583899, 2023). "BRAF is the most commonly mutated gene involved in the development of melanomas, but other RAS superfamily members (HRAS, NRAS, and KRAS) also contribute to the initiation, progression, aggressiveness, and response to the therapy of cutaneous melanoma." (PMID 36765834, 2023). "In this way, pharmacological inhibition of AURKA by MLN8237 (alisertib) resulted in the reduction of melanoma cell proliferation and induced senescence and apoptosis in cells with BRAF and NRAS mutation, and in vemurafenib (BRAF inhibitor) resistant cells." (PMID 37259298, 2023). "Mutations in genes involved in the MAPK pathway are most common in melanoma with changes in mitochondrial function, including activating mutations in the BRAF gene, NRAS gene and tyrosine kinase (such as KIT) and inactivating mutation in the NF1 gene." (PMID 37221594, 2023). "In NRAS-driven melanomas, the overexpression of growth factor receptor-binding protein 2-associated protein 2 (GAB2) has been reported to enhance tumor formation and angiogenesis in vivo." (PMID 36901857, 2023). "Wild-type RAF isoforms function as homo- and heterodimers, and BRAF/CRAF heterodimers drive ERK signaling downstream of mutant NRAS in MEKi-sensitive melanoma cells." (PMID 36765910, 2023). "Melanoma frequently harbors BRAF, NRAS, or KIT mutations which influence both tumor development and treatment strategies." (PMID 37403699, 2023). "Overall, our results point in the direction that p38 induces tumor suppressive effects in NRAS-mutant melanoma at least partially through the route of suppressed autophagy." (PMID 36765834, 2023). "In the large phase II trial, tunlametinib, in >80 patients with NRAS-mutant melanoma (NCT05217303) who had previously received immunotherapy, the confirmed ORR was 39.1% (95% CI, 27.1 to 52.1) with a median DOR of 6.1 months (95% CI, 4.2 to 8.9)." (PMID 37370834, 2023). "In patients with NRAS-mutant melanoma, tunlametinib showed a favorable PK profile, acceptable tolerability, and encouraging anti-tumor activity at the recommended phase II dose level in a phase I study." (PMID 37370834, 2023). "It is interesting to note that different melanoma subtypes are characterized by different frequencies of BRAF and NRAS mutations." (PMID 37627054, 2023). "Using digital droplet PCR, CSF-ctDNA analysis detected BRAF and NRAS mutations in LMM and melanoma brain metastasis patients." (PMID 36980770, 2023). "In addition, other combinatorial approaches using MEKi such as the addition of panRAF inhibitors, ERK inhibitors, BET inhibitors, or PI3K inhibitors could be a step forward for having an effective therapeutic weapon in the fight against aggressive NRAS-mutated melanomas." (PMID 38067230, 2023). "We then aimed to identify the role of MALAT1 in the clonogenic potential of NRAS-mutant melanoma cells using a colony formation assay in the D04 cell line." (PMID 37235843, 2023). "The prevalence of co-altered mutations in the MAPK pathway in melanomas was the highest among the cancer types we analyzed and was 61.1% for HRAS, 59.4% for KRAS, and 31.3% for NRAS-mutant tumors." (PMID 37503077, 2023). "In a large cohort of mucosal melanomas, 3% of AMs showed BRAF, 10% showed NRAS, and 19% showed KIT mutations." (PMID 35642348, 2023). "NRAS-mutant melanomas are also resistant to MEKi and median progression-free survival (PFS) in clinical trials was limited to 2.8–3.25 months at best." (PMID 36765910, 2023).
melanoma (continued). "To further investigate the anti-cancer effects of MALAT1 inhibition in MALAT1-downregulated cancer, we applied systemic MALAT1-ASO treatment in xenograft mouse models with NRAS-mutant melanoma tumors." (PMID 37235843, 2023). "By contrast, another retrospective study for checkpoint inhibitor showed a worse survival for NRAS‐mutant melanoma than NRAS wildtype (21 vs. 33 months, p = 0.034), although both groups showed comparable response rates." (PMID 37403699, 2023). "This mutation scenario was also proven in our cohort, with melanomas in face and scalp mostly carrying BRAF V600K, NRAS and NF1 mutations, whereas only one out of eight patients (12.5%) carried the BRAF V600E mutation." (PMID 36765773, 2023). "In this study, as an extension to our previous work on head and neck mucosal melanomas, we aimed to investigate the BRAF, NRAS, KIT, TERT and GNAQ/GNA11 mutation status of 15 AMs, as well as their clinicopathologic features." (PMID 35642348, 2023). "Previously, we showed that p38 acts as a tumor suppressor in vitro and in vivo with respect to NRAS-mutant melanoma." (PMID 36765834, 2023). "Patients with melanomas harboring BRAF V600 or NRAS Q61 alterations have a shorter time to treatment failure than those with NF1 or other driver alterations." (PMID 37475035, 2023). "As we wanted to rule out effects specific to cell line groups (i.e., 130429 and 160915), we performed the assay on a different patient-derived NRAS-mutant melanoma cell line 130227." (PMID 36765834, 2023). "Encorafenib combined with binimetinib was well tolerated in a phase III trial showing potent antitumor activity in BRAF-mutant melanoma, making a rapid evaluation in NRAS-mutant melanoma imminently feasible." (PMID 38067230, 2023). "HBL cells belong to the triple-WT molecular subtype of melanomas (NRAS, BRAF and NF1 WT) and they respond to stimulation with melanocortin agonists with strong increases in both cAMP and ERK1 and ERK2 activity." (PMID 37762683, 2023). "Taken together, these findings indicate that miR-708 exerts anticancer effects on NRAS-driven melanoma, AML, and NSCLC cell lines." (PMID 37083947, 2023). "ERK inhibitor ulixertinib resulted in 18% partial response in NRAS mutant melanoma patients in a phase I clinical trial." (PMID 37221195, 2023). "The most frequently mutated positions in our cohort of 524 primary melanomas included nucleotides in well‐known driver genes such as BRAF, NRAS and TERT, and a similar frequency of RQCD1 p.P131L mutations has been described in another primary melanoma cohort." (PMID 36219477, 2023). "Regarding the prevalent melanoma-related mutated genes BRAF, NRAS and NF1, 38 known oncogenic mutations were found in all 46 melanoma samples." (PMID 36765773, 2023). "Our observations of reversing MEK inhibitor resistance using low-dose anisomycin in NRAS-mutant melanoma cells led us to investigate the tumor suppressing activity of p38." (PMID 36765834, 2023). "We used The Genotype-Tissue Expression (GTEx) database (n = 1305) for the analysis of non-cancerous patient skin samples and The Cancer Genome Atlas (TCGA) database (n = 366) for the analysis of NRAS- and BRAF-mutated melanoma patient samples." (PMID 37235843, 2023). "MALAT1-ASO treatment strongly impaired cell growth and colony formation in a large panel of NRAS- and BRAF-mutated melanoma cells, including MEKi-resistant cells." (PMID 37235843, 2023). "Meanwhile, melanomas arising in high CSD skin, which present as lentigo maligna melanomas, contain more NRAS and KIT mutations." (PMID 37841001, 2023).